CD4 (CD4 molecule)
Diseases named in the same sentence as CD4 in open-access papers (continued):
Sharing a sentence is not in itself a finding about the gene and the disease.
co-infection (continued). "Several studies have reported that older age, male gender, low baseline count of CD4 T cell, advanced clinical stage, high viral load, and TB co-infection are associated with a higher risk of death." (PMID 33684169, 2021). "The multivariate model of advanced liver fibrosis showed HCV coinfection as the main risk factor (OR, 20; 95% CI, 4–102; p < 0.001); CD4 cell count was a protective factor." (PMID 34064387, 2021). "The objective of this study was to determine the association of HBV co-infections with CD4 count and viral load levels in response to antiretroviral treatment among HIV patients attending comprehensive care clinics in Makueni County (Kenya)." (PMID 33889269, 2021). "CD4+ T cell counts were significantly lower in HBV patients (p = 0.025), and co-infection was associated with a poorer CD4+ T cell response to ART (AOR 0.88; 95% CI 0.79–0.98; p = 0.030)." (PMID 33206693, 2020). "In this study, the clinical course of severe cases was over 3 weeks, and severe cases had a potentially high risk of co-infection with other pathogens due to critical exhaustion of CD4+ and CD8+ T cells." (PMID 32983157, 2020). "The skewed CD4/CD8 T cell ratio in blood of HIV+ women was mirrored in the cervical mucosa and HPV co-infection was linked to lower levels of mucosal CD4 T cells in HIV+ women (%median: 22 vs 32; p = 0.04)." (PMID 33007050, 2020). "Femaleness, the lower CD4+ T-cell count at baseline, an advance stage at baseline, and coinfection with HBV were risk factors for persistent cytopenia after HAART, which suggested the importance of starting HAART early in cytopenia patients with HIV infection." (PMID 32090076, 2020). "co-infection remained significantly associated with higher CD4+ T cell counts (aOR 1.22, 95% CI 1.00–1.50, p = 0.049)." (PMID 31479472, 2019). "We have recently described a new tractable mouse model to study reactivation of LTBI, following the loss of CD4+ T cells similar to what occurs in HIV co-infection in humans." (PMID 30949177, 2019). "Lower CD4 count, co-infection with PM or TB were independent risk factors of anaemia in HIV-infected inpatients." (PMID 30816082, 2019). "Older age, female sex, longer HIV duration and HCV coinfection were associated with a higher hospitalisation risk, whereas higher CD4 nadir and antiretroviral therapy were associated with a reduced risk." (PMID 30869037, 2019). "In fact, co-infection suppresses peak joint pathology of CHIKV infection by limiting the infiltration of pathogenic virus-specific IFNγ (Th1)-producing CD4+ T cells in the joints." (PMID 30254309, 2018). "Our surprising observation that increased CD4 count correlated as a risk factor for HCV coinfection suggests that additional research is necessary to address the issue of HCV-progression in HIV-positive individuals who are receiving ART." (PMID 29487874, 2018). "The bivariate analysis result showed that residence, INH prophylaxis status, WHO clinical stage and CD4 level at ART initiation were associated with TB-HIV/AIDS co-infection." (PMID 29954451, 2018). "In our study, a higher CD4+ T cell count (>200 cells/μL) was associated with a decreased risk of HCV or HBV coinfection among HIV-positives." (PMID 29487874, 2018). "In the current study, the important factors associated with TB/HIV co-infection were low CD4 count (<200cells/mm3) and advanced WHO stage (3 & 4)." (PMID 30281631, 2018). "An increasing number of HHV co-infections was also independently associated with poorer CD4 T-cell recovery following 12 months of ART; however, the effect of K/T ratio on CD4 T-cell recovery was only marginal." (PMID 29016635, 2017). "HCV or HBV coinfection and development of skin rash were independently associated with the development of hepatotoxicity, whereas higher baseline CD4 counts and use of NVP were independently associated with skin rashes within 4 weeks of cART initiation." (PMID 28222098, 2017).
co-infection (continued). "In the bivariate (crude) Cox-regression analysis, educational status, occupation, baseline WHO clinical stage, TB co-infection, OI prophylaxis intake and CD4 count were showed association at P-value of less or equal to 0.2." (PMID 29267292, 2017). "In multivariate analysis, higher K/T ratio (p = 0.03) and increasing number of HHV co-infections (p<0.001) were independently associated with poorer CD4 T-cell recovery following 12 months of ART initiation." (PMID 29016635, 2017). "This phenomenon has been widely studied using different approaches, and its pathogenesis is known to be related to older age, nadir CD4 T-cell count, reduced thymic function, co-infection with hepatotropic viruses, and multiple genetic variants." (PMID 28388647, 2017). "Active TB with HIV co-infection was associated with a higher percentage of MTB-specific CD4+ T-cells secreting IFN-γ alone expressing PD-1 compared to all other groups, p = 0.019." (PMID 26756579, 2016). "Increased expression of PD-1 on CD4+ MTB-specific IFN-γ-secreting T-cells was associated with HIV co-infection and correlated with VL." (PMID 26756579, 2016). "The HI virus attacks CD4+ T cells, and a co-infection renders the patients highly susceptible to TB." (PMID 27242801, 2016). "HIV-TB co-infection was consistently and independently associated with a reduced frequency of CD4+ IFN-γ and IL-2-dual secreting T-cells and the proportion correlated inversely with HIV viral load (VL)." (PMID 26756579, 2016). "Increased risk of developing KS and PEL associated with low CD4+ T cell count indicates that immune suppression associated with HIV co-infection plays essential roles in KSHV induced pathologies." (PMID 26913028, 2016). "Although we have not evaluated the secretion of inflammatory cytokines by these cells, our data suggest that co-infection by HTLV-1 is associated with higher frequency of CD4+CD25HighFoxp3+, broadly defined as potentially inflammatory Treg cells." (PMID 26329520, 2015). "Using a multivariate model, older age, presence of Hepatitis B or/and C virus co-infection and lower CD4 cell count were associated with solid NADC incidence." (PMID 26442127, 2015). "In summary, HIV co-infection with MTB was associated with a decrease in the number of cytokines secreted from HIV-specific CD4+ T cells." (PMID 25781898, 2015). "A meta-analysis of 8 trials, involving 6,206 patients concluded that coinfection by HCV is an independent factor associated with poorer CD4 recovery, in comparison with HIV infection alone." (PMID 26355305, 2015). "We examined the influence of several factors including, age, sex, CD4 cell count, residence, geographical region and number of sexual partners on the risk of co-infection with HBV or HCV." (PMID 26371878, 2015). "A similar pattern has been reported in HIV/TB co-infection where HIV was associated to a reduction in CD4+ counts together with a reduced sputum smear positivity rate compared to HIV-/TB patients." (PMID 26248316, 2015). "Longer time under suppressive ART was also associated with a greater chance of AR, but logistic regression identified coinfection by HCV as the main factor associated with abnormal CD4/CD8 ratio." (PMID 26355305, 2015). "Risk factors significantly associated with HIV/HBV co-infection were being male, having a lower CD4 count, living in an urban setting and coming from the Eastern region of Cameroon." (PMID 26371878, 2015). "Compared to prior studies, we present an analysis of antibody responses to a larger set of P. falciparum antigens during co-infection and characterize the B cell compartment, CD4+ T cell counts and HIV viral loads associated with antibody breadth." (PMID 25928218, 2015). "We reported an inverse association between the prevalence of M. tuberculosis/HIV co-infection and CD4 cell count, such that the risk of co-infection increased as the CD4 cell count decreased." (PMID 25358465, 2014).
co-infection (continued). "At baseline, different inflammatory markers were strongly associated with HCV co-infection, lower CD4 counts and with cART regimens (being higher in PI-treated individuals), but poorly correlated with detection of markers of residual viral replication." (PMID 25462535, 2014). "High CD4 counts in patients with HCV/HIV coinfection have been associated with a reduced risk of substantial increases in HA levels and hepatic fibrosis." (PMID 24865485, 2014). "Our study highlights the association of filarial co-infection with a profound impairment in TB - antigen specific CD4+ Th1 and Th17 responses." (PMID 25211342, 2014). "The inflammatory profile in treated HIV-infected individuals showed a complex association with HCV co-infection, the levels of CD4 T cells and the cART regimen." (PMID 25462535, 2014). "Many studies have shown that GBV-C and HIV coinfection was associated with higher CD4+ cell count and lower HIV load." (PMID 24693316, 2014). "The present study also depicts the association of lower CD4+ T-cell count with HIV/HBV co-infection, which is in accordance with one of the first such studies from Nigeria." (PMID 24023688, 2013). "Helminth infection was associated with a higher risk for malaria, whilst low CD4 counts were linked to a higher risk of malaria and co-infection." (PMID 23967365, 2013). "We also analyzed HCV/HIV coinfection in a Daudi B-cell line expressing CD4 and susceptible to both HCV and HIV infection." (PMID 24098405, 2013). "Since lower CD4+ T-cell count was associated with HIV/HBV co-infection, we further analyzed the variation of CD4+ T-cell count with HBV DNA load among the HBeAg positive and HBeAg negative patients." (PMID 24023688, 2013). "The last cell count (fourth year) clearly indicated that HCV co-infection was associated with fast decline of both CD4+ and CD8+ cells count than HIV mono-infected groups (CD4+: 211 Vs 314; P < 0.004 and CD8+: 772 Vs 1092; P < 0.002) respectively." (PMID 23679118, 2013). "In multivariate analysis, only CD4+ lymphocyte count was found to be independently associated with TB-HIV co-infection." (PMID 22738361, 2012). "In multivariate analysis, CD4+ lymphocyte count was found to be independently associated with TB/HIV co-infection." (PMID 22738361, 2012). "HIV/HTLV-1 co-infection is associated with increased CD4 counts, which complicates the decision when to start treatment." (PMID 22194980, 2011). "Recent studies of HIV/Plasmodium falciparum co-infection have reported significant interactions of these pathogens, including more rapid CD4+ T cell loss, increased viral load, increased immunosuppression, and increased episodes of clinical malaria." (PMID 19774084, 2009). "Sub-clinical hepatotoxicity was significantly associated with HIV co-infection (p = 0.002), concomitant drug intake (p = 0.008), and decrease in CD4 count (p = 0.001)." (PMID 18350147, 2008). "However, stratified analysis revealed that co-infection was significantly associated with lower resistance in patients with a treatment duration of 6-12 months (OR = 0.24, P = 0.001) and those with CD4 + Count ≤ 350 cells/μL (OR = 0.38, P = 0.001)." (PMID 41883798, 2026). "Baseline HBsAg quantitative and CD4 T cell counts are associated with HBsAg loss in individuals with HIV/HBV coinfection after combined antiretroviral therapy and may inform treatment decisions." (PMID 40046188, 2025). "Furthermore, HTLV/HIV co-infection is associated with a heightened prevalence of activated CD4+ T cells expressing CD45RO and CD25." (PMID 40284988, 2025). "Interestingly, this study demonstrates that H. pylori co-infection was positively associated with elevated CD4+ T cell counts and reduced HIV viral load in HIV-positive patients, consistent with a previous study." (PMID 38494500, 2024). "Secondly, these KPs might have more advanced HIV disease progression, lower CD4 counts, or poorer overall health, which could elevate their susceptibility to TB co-infection." (PMID 38995935, 2024).
co-infection (continued). "Probiotics also may promote epithelial healing by altering intestinal flora and reduce the risk of viral transmission and hospitalization for coinfection by preventing the decline in CD4+ cell count." (PMID 37382253, 2023). "Similarly, low pre-ART CD4 + cell count and coinfection with HCV were found to be associated with suboptimal immune recovery in this population." (PMID 35135485, 2022). "Reduced immunity due to the reduction of CD4 + T-cells may explain the higher risk of recurrent TB in patients with an HIV co-infection." (PMID 35332864, 2022). "However, in a cohort study of HIV patients in Asia, HIV/HCV co-infection was found to be associated with lower CD4 cell recovery." (PMID 36417469, 2022). "Finally, STI–HIV coinfection is significantly associated with persistent immune activation and poorer CD4+ T cell recovery." (PMID 35027093, 2022). "However, HIV coinfection was associated with highly significant further reduction of the lung CD4/CD8 ratio (0.5, P < 0.0001 vs. HIV– participants), indicating an additional profound impact of HIV infection on lung T cells in these diseased participants." (PMID 33848273, 2021). "Moreover, HIV-positives with CD4+ T cell counts of >200 cells/μL were associated with a lower risk of coinfection with HCV." (PMID 35222296, 2021). "Therefore, this study was conducted to determine the association of HBV co-infections with CD4 count and viral load levels in response to antiretroviral treatment among HIV patients attending comprehensive care clinics in Makueni County (Kenya)." (PMID 33889269, 2021). "and HIV co-infection may be caused by a low immune response, particularly a lower of CD4+ T cells in patients with HIV, leading to the uncontrolled number of malaria parasites, which may lead to SM23,36,47–49." (PMID 34404814, 2021). "Indeed, CMV seropositivity is associated with immunosenescence and our studies in HIV infection demonstrated that CMV coinfection is associated with elevated CD57 expression on both CD4 and CD8 memory T cells in treated HIV infection." (PMID 33868264, 2021). "Both, iatrogenic immune suppression with tacrolimus (FK506) that mainly affects CD4+ T cell activation and expansion after EBV infection of humanized mice, and CD4+ T cell depletion by HIV co-infection leads to elevated viral loads and increased EBV associated B cell lymphoma formation." (PMID 33833760, 2021). "In addition, an association of lower CD4+ counts at the time of co-infection diagnosis and mortality in the reactivation group was confirmed for the first time to our knowledge using a multivariate analysis." (PMID 34591866, 2021). "Similarly, lower CD4+ cells numbers at co-infection diagnosis and male sex were associated with higher lethality in CDR." (PMID 34591866, 2021). "In our case study, we also tried to find the reason of coinfection; this was probably due to the depressed cellular immunity, skin abruptions, and acquired dermatophytic infection which is prevalent and associated with lower CD4+ T cell count." (PMID 33763264, 2021). "Lower CD4+ cells count at co-infection diagnosis was independently associated with reactivation." (PMID 34591866, 2021). "In addition, although it is the largest known sample, considering the limited size of CDR group and interval between co-infection and reactivation diagnoses, associations of CD4+ with reactivation and death need to be confirmed in future studies." (PMID 34591866, 2021). "In addition, we found that those with CD4 levels < 100 who were female or who also had HCV coinfection were at an especially high risk of anemia." (PMID 32197585, 2020). "In addition, HIV positive women with less CD4 cell count and in the final clinical stage or suffered from a co-infection were also associated with depressive symptoms." (PMID 32742296, 2020). "As well as a low CD4 count predisposing to coinfections that may trigger inflammation, the inflammatory response itself might potentiate CD4 T-cell loss." (PMID 32103268, 2020).
co-infection (continued). "Indeed, impaired CD4+ T cell immunity due to HIV coinfection in individuals with LTBI is one of the underlying causes of TB reactivation." (PMID 33083030, 2020). "Hence, the MGL approach is a rapid approach to evaluate phylogenies in light of a variety of attributes, both discrete (e.g. co-infection, risk group, geography) and continuous (e.g. neutralization breadth, CD4+ T-cell count)." (PMID 31700680, 2019). "Lower CD4 counts, co-infection with TB or PM were independent risk factors for anaemia." (PMID 30816082, 2019). "Previous findings from Cameroon relate lower CD4 counts to increased risk of HBV co-infection." (PMID 29338763, 2018). "Additionally, an increasing number of HHV co-infections compared to participants with a single HHV co-infection was found to be associated with on average 137–160 cells/ul decrease in CD4 T-cell counts beyond the initial 12 months of ART." (PMID 29016635, 2017). "We hypothesized that in the setting of MTB infection, HIV co-infection would be associated with a reduced frequency of particular CD4+ MTB-specific T-cell cytokine secreting subsets and that this might serve as a correlate of MTB infection containment." (PMID 26756579, 2016). "Interestingly, we observed a significant association between having a lower CD4 cell count and risk of co-infection." (PMID 26371878, 2015). "In addition, coinfection by HCV is recognized as a potential cause of deficient increase in CD4+ cells, after suppressive ART." (PMID 26355305, 2015). "A recent study reported higher co-infection risk with higher CD4 counts." (PMID 25993501, 2015). "It is therefore logical that those with a lower CD4 count should be at higher risk of co-infection." (PMID 26371878, 2015). "Similarly, duration of ART, co-infection with TB, CD4 + T-cell count and anaemic status were associated with virologic failure." (PMID 24479873, 2014). "Similarly, Strongyloides co-infection was associated with decreased frequencies of CD4+ T cells co-expressing TNF-α/IFN-γ or IL-2/IFN-γ/TNF-α at baseline in comparison to individuals with active TB only." (PMID 25211342, 2014). "However, in HIV/HCV co-infection scenario, the systemic immune dysfunction and CD4+ T cell depletion associated with HIV, remains the major factor in HCV persistence and chronic liver inflammation." (PMID 25528160, 2014). "Thus, HCV/HIV coinfection was associated with an enrichment of FoxP3+ subsets within the CD4 T cell compartment and relative preservation of FoxP3+ Tregs in circulating lymphocytes." (PMID 25071758, 2014). "We examined the relative replicative fitness of phenotypic SIV variants using both in vitro and in vivo co-infections in order to examine the impact of competition and target cell availability on relative viral replication and CD4+ T cell decline during the early stages of infection." (PMID 20942954, 2010). "Additional analysis of CD4+ T cell subsets as well as CD8+ T cell subsets in the rhesus co-infection model could further define the loss of parasite-specific and SIV-specific effector functions." (PMID 19774084, 2009). "Moreover, an increased risk of liver fibrosis in HIV-1/HCV co-infection may be associated with reduced CD4 + T cell counts, elevated lipopolysaccharide levels, and/or the depletion of hepatic Kupffer cells." (PMID 37298575, 2023). "The study suggested that age and CD4+ T cell count may affect the risk for HIV-HCV coinfection." (PMID 35222296, 2021). "However, VL itself might play a role: Leishmania co-infection could enhance viral replication and immune activation, thus contributing to CD4 T-cell depletion and increasing the risk of reactivation of latent infections." (PMID 25358548, 2014). "Moreover, variable levels of HIV RNA may confound the association of HIV co-infection with CD4+ T-cell count increase." (PMID 22703595, 2012). "TB-HIV coinfection was identified in 55.3% of cases, with 83.5% of these patients having CD4+ T-cell counts ≤ 200 cells/mm3." (PMID 41723884, 2026).